PANX1 (pannexin 1)
Diseases named in the same sentence as PANX1 in open-access papers (continued):
Sharing a sentence is not in itself a finding about the gene and the disease.
Sepsis (continued). "Panx1 contributes to brain dysfunction in sepsis-induced encephalopathy by promoting pyroptosis." (PMID 37711629, 2023). "Notably, ablation of PANX1 has been shown to reduce the level of pyroptosis and enhance resistance to sepsis." (PMID 37711629, 2023). "However, further research is needed to fully understand the complex interplay between Panx1, platelet function, and microcirculation in the context of sepsis, ultimately leading to the development of targeted therapies." (PMID 37711629, 2023). "This article aims to shed light on Panx1’s potential therapeutic value against sepsis-induced MODS." (PMID 37711629, 2023). "Based on our findings, the PANX1‐IL‐33 axis may represent a new target for treating sepsis after LT." (PMID 35593197, 2022). "In this study, we examined the role of the PANX1–IL‐33 axis in protecting against sepsis caused by a gram‐negative bacterial infection in an independent LT cohort." (PMID 35593197, 2022). "In human studies, we investigated the PANX1‐IL‐33 axis in patients with sepsis." (PMID 35593197, 2022). "Consequently, the specific roles of PANX1 in sepsis and the related organ injury remain largely unclear." (PMID 35593197, 2022). "The peak AST level during sepsis was negatively correlated with donor PANX1 expression prior to LT." (PMID 35593197, 2022). "Furthermore, we analyzed the correlation between PANX1 levels and peak AST levels in 13 patients with sepsis to further study the role of PANX1 in sepsis‐induced liver injury." (PMID 35593197, 2022). "However, complete disruption of PANX1 function in vivo impaired host immune defences against virulence factors, which led to decreased numbers of activated immune cells and clinical sepsis." (PMID 35593197, 2022). "When CASP11 was activated by LPS, pyroptosis and susceptibility to sepsis can be induced by the non-canonical inflammasome through pannexin-1 and the P2X7 signaling pathway, which was downstream of CASP11." (PMID 36250055, 2022). "Although Panx1 was readily detectable in the serum of normal healthy female mice, its circulating levels were significantly reduced at 24 h post the onset of sepsis." (PMID 30655582, 2019). "Here we further elucidated the possible role of Pannexin 1 (Panx1) hemichannel in lethal sepsis by assessing its expression along with the impact of a Panx1-specific mimetic inhibitory peptide, 10Panx, on macrophage hemichannel activity in vitro and animal sepsis lethality in vivo." (PMID 30655582, 2019). "It suggested that the 10Panx’s macrophage hemichannel-enhancing properties in vitro correlated with its deleterious impact on lethal sepsis in vivo, enforcing the notion that excessive macrophage Panx1 hemichannel activation contributes to the pathogenesis of lethal systemic inflammation." (PMID 30655582, 2019). "However, the expression profile of another class of hemichannel protein, Pannexin 1 (Panx1), during lethal sepsis remains poorly understood." (PMID 30655582, 2019). "Given the absence of Cx43-and Cx45-based hemichannels, the increase in P2X7R and Panx1 expression may represent a systemic response to sepsis, as both proteins are known to be upregulated during inflammatory conditions and contribute to immune cell recruitment and inflammasome activation." (PMID 40066286, 2025). "Given that excessive or dysregulated pyroptosis can amplify tissue damage in sepsis, neuroinflammation, or inflammatory bowel disease, the potential regulatory axis of Panx1–calcium–calpain-1 could represents a novel mechanism by which immune responses are modulated during inflammation." (PMID 40978734, 2025). "However, genetic disruption of Panx1 expression rendered animals resistant to lethal endotoxemia, but impaired inflammation-mediated microbial clearance and ultimately worsened the outcome of lethal sepsis." (PMID 39763679, 2024). "Overall, Panx1 may be a promising target for sepsis-induced MODS." (PMID 37711629, 2023).
Sepsis (continued). "However, given that Panx1’s role may vary during different phases of sepsis, more investigations are required before interventions against Panx1 can be applied in clinical." (PMID 37711629, 2023). "In the early stages of sepsis, the interaction between P2X7 and Panx1 can positively regulate interleukin-33 (IL-33)." (PMID 41041630, 2025). "However, it is unclear whether PANX1 also plays a role in regulating adaptive immunity in the defence against other infections, such as sepsis caused by gram‐negative bacteria (GNB) infection." (PMID 35593197, 2022). "Therefore, here we sought to examine whether Panx1 protein was inducible in macrophage cultures, and how 10Panx influences macrophage hemichannel activation in vitro and affects the sequelae of lethal sepsis in vivo." (PMID 30655582, 2019). "Though inhibitors of Panx1 show promising outcomes in animal models of sepsis, there is still a long way before clinical application in treating sepsis, as no clinical trials have been reported yet." (PMID 37711629, 2023). "However, it’s not clear whether Panx1 is potential as a therapeutic target for sepsis-induced MODS." (PMID 37711629, 2023).
migraine (13 papers, 2013 to 2024). "In a rat model of migraine, activation of Panx1 channels on peripheral trigeminal neurons caused cerebrovascular dysregulation with changes suggestive of aura followed by headache." (PMID 23898301, 2013). "Notably, a recent study demonstrates that CSD causes migraine-like headaches by triggering the neuronal pannexin-1 (Panx1) mega channel opening, leading to potentiation of neuroinflammatory responses and sustained activation of trigeminal afferents." (PMID 32070042, 2020). "Cortical spreading depression (CSD), the electrophysiological equivalent of migraine aura, results in opening of pannexin 1 megachannels that release ATP and triggers parenchymal neuroinflammatory signaling cascade in the cortex." (PMID 39044141, 2024). "These advances open the exciting possibility of developing Panx1 inhibitors as migraine prophylactic drugs; especially considering some Panx1 inhibitors such as carbenoxolone, probenecid and mefloquine are already clinically registered medicines." (PMID 34858192, 2021). "In summary, our present study reveals a novel migraine aura mechanism by which CSD induces SFK-dependent Panx1 channel activation via NR2A." (PMID 32070042, 2020). "The present study reveals a novel migraine aura mechanism by which CSD induces SFK-dependent Panx1 activity, which, at least in part, is regulated by NR2A-containing receptors." (PMID 32070042, 2020). "CSD is the electrophysiological equivalent of migraine aura which results in opening of Panx1 megachannels, neuronal HMGB1 release and induction of neuroinflammatory cascades in astrocytes that eventually result in neurogenic inflammation, trigeminal activation and headache." (PMID 39044141, 2024). "Interestingly, in the absence CSD, it has been shown that parenchymal inflammatory signaling pathway can be initiated via activation of neuronal Panx1 channels, this time, by migraine triggers such as sleep deprivation." (PMID 34858192, 2021). "Together, the evidence suggests that Panx1 channels are important conduits in the transmission of pain, and that they may represent a novel therapeutic target for different kinds of pain, including neuropathic pain, migraine with aura, and orofacial pain." (PMID 34068881, 2021). "Indeed, there is evidence that Panx1 channels may play a role in orofacial pain and migraine with visual or sensory aura." (PMID 34068881, 2021). "Therefore, SFK may serve as an intermediate molecule in the signal transduction pathway resulting in the Panx1 opening, possibly in the context of migraines." (PMID 32070042, 2020).
atherosclerosis (12 papers, 2014 to 2026). A disease characterized by the build-up of fatty material and calcium deposition in the arterial wall resulting in partial or complete occlusion of the arterial lumen. "Ubiquitous deletion of Panx1 impaired lymphatic function resulting in reduced serum triglyceride (TG) levels in atherosclerosis‐prone apolipoprotein E‐deficient (Apoe−/−) mice." (PMID 39085909, 2024). "Endothelial cell-specific deletion of Pannexin1 (Panx1) in apolipoprotein E-deficient (Apoe-/-) mice increased atherosclerosis, suggesting a protective role for Panx1 channels in arterial endothelial function." (PMID 39775604, 2024). "On the one hand, atherosclerosis-susceptible mice with a specific deletion of Panx1 in endothelial and monocytic cells (Tie2-CreTg Panx1fl/fl Apoe−/−) displayed increased atherogenesis, pointing to a protective role for Panx1 in these cells." (PMID 34072103, 2021). "Moreover, Panx1 deficiency has been shown to be associated with atherosclerosis and white adipose tissue accumulation as well as with lymphatic dysfunction." (PMID 32023876, 2020). "Using atherosclerosis-susceptible mouse models with ubiquitous deletion of Panx1 (Panx1−/−Apoe−/−) or with Cre recombinase-mediated deletion of Panx1 in endothelial cells and monocytes (Tie2-CreTgPanx1fl/flApoe−/−; Panx1delApoe−/−), we identified a novel role for Panx1 in the lymphatic vasculature." (PMID 29057961, 2017). "Third, both augmented Panx1 channel expression and elevated levels of lysophospholipids have been independently reported to be associated with insulin resistance, a common health problem linked to a wide array of pathologic conditions, including type 2 diabetes, hypertension, and atherosclerosis." (PMID 40309905, 2025). "In contrast, Panx1 is protective both in the initial development of atherosclerosis and during pre- and post-conditioning to coronary ischemia." (PMID 41569301, 2026). "In male mice deficient of Apolipoprotein E, the most common murine model of atherosclerosis, endothelial and monocyte-specific (Tie2 Cre) Panx1 deletion increased the formation of atherosclerotic plaques in carotid arteries." (PMID 41569301, 2026). "Together these observations suggest that lymphatic Panx1 exerts a protective effect against atherosclerosis progression in female mice, highlighting the complex interplay between sex-specific factors and disease pathogenesis." (PMID 39775604, 2024). "We have previously shown that atherosclerosis was enhanced in Tie2-CreTgPanx1fl/flApoe-/- mice, pointing to an atheroprotective role for Panx1 in endothelial and/or monocytic cells." (PMID 39775604, 2024). "Altogether, our results reveal differential sex-dependent effects of Panx1 in lymphatic endothelium on the progression of atherosclerosis." (PMID 39775604, 2024). "Here, we investigated the role of Panx1 in lymphatic endothelial cells (LECs) in the initiation and the progression of atherosclerosis." (PMID 39775604, 2024). "The present study was undertaken to study the effects of Panx1 deletion in LECs on the initiation and the progression of atherosclerosis in male and female mice." (PMID 39775604, 2024). "First, lymphatic drainage was impaired only in male mice upon Panx1 deletion from LECs, which is consistent with the results obtained in our previous study in atherosclerosis‐prone male mice with ubiquitous Panx1 deletion." (PMID 39085909, 2024). "To investigate if deletion of Panx1 channels in LECs affects the progression of atherosclerosis in female mice, we used the same protocol as for the male mice." (PMID 39775604, 2024). "To investigate a potential contribution of Panx1 in LECs in the initiation of atherosclerosis, we induced Panx1 deletion with tamoxifen in 6 weeks-old Panx1LECdelApoe-/- mice and control Panx1fl/flApoe-/- mice." (PMID 39775604, 2024). "Secondly, a role for lymphatic Panx1 in atherosclerosis was dissected using two different mouse models." (PMID 34072103, 2021).
atherosclerosis (continued). "The role of Cxs in atherosclerosis has been extensively studied for many years, while a potential involvement of Panx1 has only recently been highlighted." (PMID 34072103, 2021). "For instance, in atherosclerosis-prone mice fed a high cholesterol diet, ubiquitous Panx1 deletion was shown to reduce serum triglyceride and FFA levels." (PMID 32023876, 2020). "Further experiments might elucidate a possible compensatory role of Cx47 in the context of Panx1 deletion and atherosclerosis." (PMID 39775604, 2024). "Accordingly, in line with the previous studies, we provide additional support for the hypothesis that PANX1 is the main conduit for hypoxia-induced ATP release from RBCs in this mouse model of atherosclerosis." (PMID 39678689, 2024). "Atherosclerotic lesion development in response to high cholesterol diet was enhanced in Tie2-CreTgPanx1fl/flApoe−/− mice as compared to Panx1fl/flApoe−/− controls, pointing to a protective role for Panx1 in endothelial and/or monocytic cells in atherosclerosis." (PMID 29874791, 2018). "Notably, it can be speculated that in this adenosine-mediated atherosclerosis mechanism, Panx-1 hemichannels may play a role in the release of intracellular ATP into the extracellular environment leading to the formation of adenosine." (PMID 24672487, 2014). "In summary, LEC-specific deletion of Panx1 did not alter body weight, serum lipid levels, atherosclerotic plaque burden and composition during early atherosclerosis." (PMID 39775604, 2024). "To investigate a potential contribution of Panx1 in LECs in the progression of atherosclerosis, we placed the mice on a HCD for 4 weeks to initiate the disease, then deleted Panx1 channels in LECs and studied the advanced atherosclerotic plaque burden in the aortic roots after 6 more weeks of HCD." (PMID 39775604, 2024). "Similar to the results obtained in male mice, inducing Panx1 deletion in LECs did not affect the serum lipids in female mice during the progression of atherosclerosis." (PMID 39775604, 2024). "This implies that inducing Panx1 deletion in LECs did not affect circulating lipid concentrations during the progression of atherosclerosis." (PMID 39775604, 2024). "In conclusion, while Panx1 deletion did not influence the early stages of atherosclerosis, it emerged as a factor in modulating disease progression in females." (PMID 39775604, 2024). "Although these findings strongly suggest a link between Panx1, lipid metabolism, lymphatic function and atherosclerosis, a direct role for lymphatic Panx1 in this disease has not been demonstrated yet." (PMID 34072103, 2021). "Finally, as the effects of Panx1 deletion on lymphatic function are known to be more subtle than the sizeable effects of sex on cardiovascular disease, we analyzed results onto the effects of LEC-specific Panx1 deletion on the progression of atherosclerosis separately for male and female mice." (PMID 39775604, 2024). "During early atherosclerosis induced by 6 weeks of HCD, we observed mainly sex-dependent differences rather than differences induced by Panx1 gene deletion." (PMID 39775604, 2024).
Cerebral ischemia (11 papers, 2014 to 2024). Restriction of arterial blood supply to the brain associated with insufficient oxygenation to support the metabolic requirements of the tissue. "The unique properties of Panx1 channels contribute to the profound neurotoxicity associated with this channel activation during retinal and brain ischemia." (PMID 24575045, 2014). "Similar results were observed in an experiment that selectively knocked out the PANX1 gene in mouse blood vessels to investigate the effect of PANX1 on cerebral ischemia/reperfusion injury." (PMID 37196132, 2024). "The NMDA receptor, Src, and pannexin 1 (Panx1) comprise a metabotropic signaling complex that is involved in the process of cerebral ischemia." (PMID 35264964, 2022). "The metabotropic NMDA receptor-Src-Panx1 signaling pathway exerts a pro-death effect in cerebral ischemia." (PMID 35264964, 2022). "In a rodent model of brain ischemia, pharmacological blockade and genetic ablation of Panx1 channels have been shown to improve behavioral outcomes and reduce infarct volumes." (PMID 32819386, 2020). "While several lines of evidence linking Panx1 activity with inflammation, apoptosis, and necrosis have been reported, studies investigating the effect of Panx1 in cerebral ischemia have rendered contradictory results." (PMID 28445139, 2017). "Taken together, these findings unmask important sex differences in Panx1-mediated, inflammatory and neuronal responses to cerebral ischemia." (PMID 28445139, 2017). "Endothelial Panx1 can regulate TNF-α-induced leukocyte adhesion and emigration in venules, as well as modulate pulmonary and cerebral ischemia/reperfusion injury." (PMID 35315432, 2022). "For example, Bargiotas and colleagues found that genetic deletion of Panx1 protein did not protect from middle cerebral artery occlusion (MCAO) in a mouse model of cerebral ischemia." (PMID 34068881, 2021).